CXCR3 (C-X-C motif chemokine receptor 3)
Diseases named in the same sentence as CXCR3 in open-access papers (continued):
Sharing a sentence is not in itself a finding about the gene and the disease.
tumor (continued). "The mean expression of CXCR3 (based on MFI) in CD56dimCD16− NK cells showed a higher level in the patients with tumor‐free lymph nodes (LN−) compared to the ones with tumor‐involved lymph nodes (LN+) (13.3 ± 3.73 vs. 6.48 ± 0.38, p = .02)." (PMID 38652012, 2024). "It is believed that tumor cells evolved to express some chemokine receptors, such as CXCR3, and secrete its ligand CXCL10." (PMID 38495500, 2024). "It was also found that the in vivo receptor knockdown of CXCR3 significantly lessened the spread of the tumour to the liver and lungs." (PMID 39516345, 2024). "Increased levels of IRF1 in tumor cells in this study were associated with increased secretion of IFNγ by infiltrating NK and NKT cells and with induction of apoptosis by the CXCL10/CXCR3 paracrine axis." (PMID 38396830, 2024). "The CXCL9/CXCL10/CXCR3 axis plays a role in recruiting tumor-infiltrating lymphocytes (TILs) to tumors across various cancers, indicating a potential anti-tumor function." (PMID 39409924, 2024). "For example, the CXCR3 neutralization in mc38 tumor-bearing mice diminished the efficacy of the PD-1/PD-L1 combinatorial immunotherapy by fostering CD8+ T cell exclusion from the TME." (PMID 39596815, 2024). "Consistently, the CXCL9 expression by cDC1 and CXCR3 expression by CD8+ T cells were upregulated in tumors from hsBCL9z96-treated CT26 tumor-bearing mice, as well as from MC38 tumor-bearing Bcl9/Bcl9l deficiency mice." (PMID 38811552, 2024). "Not only were we able to detect increased levels of CXCR3-expressing CD8+ T-cells after IAV infection in tumour-bearing mice, but also that blocking CXCR3 abolished the infection-induced effect of reduced tumour growth." (PMID 38271469, 2024). "In HCC, Treg recruitment via CXCR3 contributes to the immunosuppressive tumor microenvironment (TME)." (PMID 39000453, 2024). "CXCR3 is almost exclusively expressed in immune cells, and together with its ligands, it has been demonstrated to play an important role in anti-tumor T cell development in the spleen." (PMID 39885986, 2024). "Sin3B deficiency results in the upregulation of chemokines Cxcl9/10, thereby enabling the high levels of Cxcl9/10 in the tumor tissues to recruit more CXCR3‐expressing effector T cells." (PMID 39316363, 2024). "Both CD4+ and CD8+ T cells showed a significantly higher expression of CCR5 and CXCR3 in tissues compared with circulating T cells, but they were both uniformly expressed in tumor-rich areas and non-tumor tissues." (PMID 38335302, 2024). "Previous research has shown that CXCR3 is crucial for the efficacy of adoptively transferred antitumor T cells and the mediation of tumor regression following anti-PD-1 therapy." (PMID 39409972, 2024). "The CXCL9, CXCL10 and CXCL11/CXCR3 axes have been demonstrated to regulate immune cell migration, differentiation, and activation, leading to tumour suppression." (PMID 39233332, 2024). "Tumors of CXCR2 KO mice had elevated CXCL13 levels to recruit B cells and B cell-derived CXCL11 in turn attracted CXCR3+ T cells into the tumor." (PMID 38786066, 2024). "Recent studies have found that the intestinal flora Akkermansia muciniphila restores the efficacy of PD-1 blockade by increasing recruitment of CCR9+ CXCR3+ CD4+ T lymphocytes to mouse tumor beds in an IL-12-dependent manner." (PMID 38790057, 2024). "Of note, one of these genes, CXCL9, which acts as a ligand of CXCR3, has been reported to have a controversial role in tumor initiation and progression, exhibiting both positive and negative prognostic values depending on the type of tumor." (PMID 38627854, 2024). "For CD8+ T cells to effectively infiltrate the tumor site, chemokine receptors, such as CXCR3, must interact with their corresponding chemokines (CXCL9, CXCL10 and CXCL11)." (PMID 39409972, 2024). "For example, TGF-β, a tumor-promoting cytokine, can block T cell trafficking by repressing CXCR3 expression." (PMID 39409972, 2024).
tumor (continued). "Despite the well-documented role of this pathway in immune cell infiltration, there is limited experimental evidence suggesting that the subversion of either CXCR3 or its ligands favors tumor immune escape." (PMID 39596815, 2024). "How significant is the direct effect of CXCL10-Fc on the ability of CXCR3+ CD8+ T cells to limit tumor growth?" (PMID 39474427, 2024). "In this study, we explored the impact of the tyrosine-sulfated CXCR3-S2 peptide trap on malignant tumor cell behavior in comparison to the wild-type CXCR3 peptide trap, using MDA-MB-231 and SKOV3 cells." (PMID 38275412, 2024). "Over time, Cxcr3 and Klrg1 were progressively decreased on tumor-specific T cells infiltrating PDA and these Cxcr3-Klrg1- T cells co-expressed PD-1 and Lag-3, markers that identify TEX cells defective in IFNγ production." (PMID 36472588, 2023). "IFNγ directly favors tumor growth control by enhancing the immunogenicity of tumor cells, induces IP-10 secretion facilitating (CXCR3+) immune cell infiltration, and can prime macrophages to an M1-like phenotype inducing proinflammatory cytokine release." (PMID 36839699, 2023). "The CXCL9 involved signaling axis (CXCL9, -10, -11/CXCR3) was found to suppress tumor progression by regulating immune cell migration, differentiation, and activation and further promoting anti-tumor immune response." (PMID 37926766, 2023). "CXCL9, CXCL10, and CXCL11 are ligands of CXCR3 and have been increasingly recognized as key regulators of the tumor microenvironment." (PMID 37686653, 2023). "We next compared tumor burden and metastasis in Cxcr3+/+ and Cxcr3−/− mice that relapsed between 35–91 days posttumor." (PMID 36472588, 2023). "We also showed that structural avidity is associated with CXCR3 expression, known to promote tumor infiltration, as well as CD103 (αEβ7) and CD49a (VLA-1) expression, both associated with tumor residency." (PMID 37280206, 2023). "Following triple treatment, the percentage and absolute number of CXCR3+ tumor-specific CD8+ T cells increased strongly in extratumoral compartments, particularly in blood." (PMID 37045833, 2023). "We imply a direct relationship between the strength of antigen recognition, CXCR3 expression and tumor infiltration, and provide a functional parameter for screening neoantigen-specific T cells for ACT." (PMID 37280206, 2023). "In both Cxcr3+/+ and Cxcr3−/− mice, tumor-infiltrating T cells upregulated PD-1 and Lag3 and lost Klrg1 as compared to splenic tetramer + T cells." (PMID 36472588, 2023). "As CD4+ Th1 cells also express the chemokine receptor CXCR3, Th1 cells enter the tumor and become activated." (PMID 37511431, 2023). "In these studies, efficacy is dependent on CXCR3 on T cells, with in vivo blockade of CXCR3 preventing orthotopic tumor regression in the presence of combined treatment." (PMID 37475035, 2023). "Mechanistically, LDRT sensitizes tumors to DPVB by recruiting stem-like CD8+ Tpex, the progenitor exhausted CD8+ T cells, from draining lymph nodes (dLNs) into the tumor via the CXCL10/CXCR3 axis." (PMID 38001101, 2023). "We identified that 60–80% of CB101-109:H-2Db tetramer + T cells expressed Cxcr3 in both spleen and tumor on day 7 posttumor." (PMID 36472588, 2023). "The receptor CXCR3 differentiates anti-tumour T cells, which are known to be significantly increased in patients at high risk of tumor recurrence." (PMID 36831346, 2023). "In-depth analysis of CXCR3 expression showed that T cells expressing CXCR3 are predominantly located in the tumor region in comparison to normal kidney." (PMID 36831346, 2023). "Herein, we analyzed CXCR3 expression on localized RCC tumor samples aiming to describe the immunological landscape as well as its prognostic value." (PMID 36831346, 2023). "Chemo-taxis of effector T cells to the tumor depends on the expression of CXCR3 on T cells and the presence of its ligands, CXCL9, CXCL10, and CXCL11 within the TIME." (PMID 37377970, 2023).
tumor (continued). "Another study revealed that IRF1 increased CD8+ T cells, NK and NKT cells migration, and activated IFN-γ secretion in NK and NKT cells to induce tumor apoptosis through the CXCL10/CXCR3 paracrine axis in HCC." (PMID 37051536, 2023). "In vivo blockade of CXCR3 prevented orthotopic tumor regression in the presence of the combination treatment, demonstrating a dependence on the CXCR3 axis for antitumor efficacy." (PMID 36881480, 2023). "In contrast, in the spleen, the Cxcr3+ Klrg1+ intermediate population was quite rare, especially when comparing to the proportion of Cxcr3+ Klrg1+ tumor-specific (tetramer-binding) T cells." (PMID 36472588, 2023). "Work in murine lymphoma tumor models has shown that the expression of CXCR3 and CX3CR1 chemokine ligands in the TME are needed for intra-tumoral accumulation of NK cells." (PMID 38022679, 2023). "CXCL10 promotes the migration of CXCR3 expressing cells, such as T cells, monocytes, NK cells, and tumor cells." (PMID 37901214, 2023). "Pancreatic stellate cells in PAAD can secrete CXCL10, which can recruit CXCR3+CD4+ cells, CXCR3+CD8+ cells and CXCR3+ Tregs into tumor tissue." (PMID 36782176, 2023). "The role of the autocrine (tumor-promoting) downstream pathways of CXCR3 in GBM has been extensively studied." (PMID 38104126, 2023). "Compared to RT/anti-PD1 treatment, blood samples from triple-treated mice showed a more than 150-fold increase in CXCR3+ tumor-specific CD8+ T cells." (PMID 37045833, 2023). "Primary tumor weights were smaller in Cxcr3−/− vs. Cxcr3+/+ relapsed mice, indicating increased tumor dissemination in Cxcr3−/− mice was not merely due to larger primary tumors and consistent with increased T cell IFNγ production at the earlier timepoint." (PMID 36472588, 2023). "The effect of K17 on immune regulation was at least partially dependent upon regulation of the CXCL9/CXCR3 axis in the tumor microenvironment." (PMID 38140561, 2023). "Here, we show in the spleen of tumor-bearing mice early on during tumor establishment, most tetramer + T cells expressed Cxcr3 and/or Klrg1 and the intermediate Cxcr3+ Klrg1 + subpopulation in the spleen is particularly enriched for tumor antigen specificity." (PMID 36472588, 2023). "Overall, our in vivo studies depleting CD4+ T cells and employing the CXCR3-blocking Ab highlight infiltration of CXCR3-expressing T cells as a potential mechanism that contributes to tumor regression in the context of this combination therapy." (PMID 36881480, 2023). "We report that, in tumours responding to atezo/bev, CXCR3+ effector memory T cells differentiated primarily towards PD1- CD45RA+ effector-memory CD8 T cells." (PMID 38030622, 2023). "Herein, we demonstrated that antagonism of CXCR3 in HPVOPC significantly slowed tumor growth in an immunodeficient model in which the pro-tumor autocrine effect of the CXCR3 axis dominates." (PMID 37686653, 2023). "The addition of TIGIT blockade to MWA resulted in the up-regulation of CXCL9 and CXCL10 expression in TAMs and their receptor CXCR3 expression in T cells, which restrain tumor growth and enhance anti-tumor immunity." (PMID 36900218, 2023). "The role of CXCR3 in tumor development remains complex, possibly depending on the isoform, cell type and microenvironment in which the receptor is expressed in." (PMID 36831346, 2023). "ThyroidPrint® is a novel q-PCR-based ten-gene classifier with its signature representing both the tumor microenvironment (CXCR3, CXCL10, CCR3, CCR7, and CXADR) and tumor epithelial cells (TIMP1, CLDN1, KTR19, AFAPL2, and HMOX1)." (PMID 37671897, 2023). "As part of the chemokine superfamily, CXCL9, in collaboration with CXCR3, activates an immune response in the tumor microenvironment to fight cancer." (PMID 37240946, 2023). "CXCR3 expression markedly dropped with increasing differentiation, as we show for subsets with exhaustion lineage markers in blood as well as tumor tissue." (PMID 37045833, 2023).
tumor (continued). "An athymic murine model demonstrates that CXCR3 antagonism does indeed inhibit tumor growth; however, CXCR3 antagonism in immunocompetent animals shows mixed results." (PMID 37686653, 2023). "Increasing evidence has shown that overexpression of CXCL9 mediates the recruitment of tumor-targeted CXCR3 + T cells and natural killer (NK) cells in various solid cancers, and thereby suppresses tumor growth." (PMID 37644593, 2023). "Tumor-specific T cells persist indefinitely (up to at least ~ 125 days posttumor) and a fraction express Cxcr3." (PMID 36472588, 2023). "Mean CXCR3 expression was significantly higher in patients with tumor recurrence compared to recurrence-free individuals (113.3 vs. 36.4, p = 0.0251)." (PMID 36831346, 2023). "In the blood, there also was a more than 150-fold increase in tumor-specific CD8+ T cells expressing the migratory chemokine receptor CXCR3." (PMID 37045833, 2023). "Together, our study supports that Cxcr3 mitigates tumor cell dissemination by impacting peripheral T cell fate rather than intratumoral T cell trafficking." (PMID 36472588, 2023). "We propose that CXCR3highCD8+ T in healthy volunteers exhibited anti-tumor capacity by CXCL10/CXCR3-activated LFA-1-ICAM-1 interaction and resulted in consequent CD8+ T cell activation." (PMID 36688994, 2023). "CXCR3 plays a crucial role in the chemotaxis of Th1 cells, NK cells and B cells, which leads to complex and divergent effects in the pathogenesis of tumor." (PMID 36690649, 2023). "It has also been reported that inhibition of the enzymatic activity of DPP4 promotes infiltration of CXCR3-expressing T cells into tumor tissues and enhances their anti-tumor effects." (PMID 37218983, 2023). "Several studies have shown that CXCR3 upregulation in vitro correlates with increased tumor proliferation, angiogenesis, and invasion in GBM." (PMID 38104126, 2023). "More recently, however, the same CXCR3 chemokine axis has also been shown to have paradoxically a pro-tumor effect, in which, in an autocrine signaling fashion, it increases tumor cell proliferation, angiogenesis, and metastasis." (PMID 37686653, 2023). "Mechanistically, LDRT sensitized DPVB by enlarging intratumoral stem-like CD8+ Tpex, which were recruited from the draining lymph nodes (dLNs) into the tumor through the CXCL10/CXCR3 axis." (PMID 38001101, 2023). "A role for Cxcr3 in T cell accumulation in tumors has been described in subcutaneous (s.c.)tumor implantation models." (PMID 36472588, 2023). "We identify a Cxcr3+ Klrg1+ intermediate T cell subpopulation in the spleen that is highly enriched for tumor specificity." (PMID 36472588, 2023). "For example, CXCL9 is a chemokine that attracts effector T cells expressing CXCR3 into the tumor microenvironment." (PMID 37926766, 2023). "Tumor growth rate was similar early on, but by day 14, tumor volumes were modestly yet significantly reduced in Cxcr3+/+ mice compared to Cxcr3−/− mice." (PMID 36472588, 2023). "To understand the basis for increased tumor cell dissemination in Cxcr3−/− mice, we quantified tumor-specific T cells in relapsed Cxcr3+/+ and Cxcr3−/− mice by tetramer staining." (PMID 36472588, 2023). "The success of trafficking mainly depends on the proper pairing between chemokines secreted by tumor cells and receptors on T cells (typically CXCR3 and CCR5)." (PMID 36765623, 2023). "Altogether, we conclude that CD43 and CXCR3 mediate tumor migration of therapy-responsive CD8+ T cells, which is critical for these cells to achieve tumor control." (PMID 36796366, 2023). "More recently, however, the same CXCL9, 10, and 11/CXCR3 axis has also been shown to have paradoxically a pro-tumor effect as well, whereby in an autocrine signaling fashion, it increases tumor cell proliferation, angiogenesis, and metastasis." (PMID 37686653, 2023). "Each cancer’s proliferative and metastatic abilities depend on the expression levels of different CXCR3 isoforms in tumor cells." (PMID 38104126, 2023).
tumor (continued). "The CXCL9, 10, and 11/CXCR3 chemokine axis has been increasingly recognized as an important regulator of the tumor microenvironment." (PMID 37686653, 2023). "Overall, these data supported that the stem-like CD8+ Tpex enhanced by LDRT were mainly recruited from the dLNs into the tumor through the CXCL10/CXCR3 axis." (PMID 38001101, 2023). "In line with the strong expansion of stem-like CXCR3+ tumor-specific CD8+ T cells in the blood circulation, CXCR3 blockade abrogated the abscopal effect in mice treated with RT/anti-PD1/IL-2c." (PMID 37045833, 2023). "Supplementation with A. muciniphila increased the recruitment of CCR9 + CXCR3 + CD4+ T lymphocytes into mouse tumor beds in an IL-12-dependent way." (PMID 37111034, 2023). "The CXCL9, -10, -11/CXCR3 axis regulates immune cell migration and activation, including that of CTLs and NK cells, which inhibit tumor development." (PMID 37777634, 2023). "Immunofluorescent (IF) staining showed that CD8 T cells were infiltrating the tumor parenchyma in both Cxcr3+/+ and Cxcr3−/− mice." (PMID 36472588, 2023). "CXCR4 and CXCR3 were regarded to play important role on the homing and infiltration of T cells to the tumor sites, and were elevated on expanded PD-1+CD8+ T cells." (PMID 37377605, 2023). "The CXCR3 axis is a critical pathway for immune cell recruitment to solid tumors that can be harnessed to increase anti-tumor responses." (PMID 37046597, 2023). "In the spleen, we detected a trend for increased frequency of tumor-specific T cells in Cxcr3−/− mice at day 21, suggesting greater T cell retention, survival and/or proliferation." (PMID 36472588, 2023). "We orthotopically implanted KPC2a tumor cells into the pancreas of Cxcr3+/+ and Cxcr3−/− mice and analyzed CD8 + tetramer + T cell phenotype on day 14 posttumor." (PMID 36472588, 2023). "Here, we identify paradoxical roles for Cxcr3 on tumor antigen-specific T cell fate and antitumor functionality during PDA progression and immunotherapy response." (PMID 36472588, 2023). "It has also been shown that tumor cells express CXCR3, and these IFN-inducible chemokines increase their chemotactic ability and are involved in cell migration and metastasis." (PMID 37218983, 2023). "The inhibition of tumor control after ACT by blocking CXCR3 was further demonstrated in two additional models using neoantigen-specific TCRs." (PMID 37280206, 2023). "While spleens were significantly larger in Cxcr3−/− vs. Cxcr3+/+ mice on day 21 post orthotopic tumor implantation, primary tumor weights were similar in Cxcr3+/+ and Cxcr3−/− mice." (PMID 36472588, 2023). "This confirms the contribution of CXCR3 in tumor homing and mechanistically links CXCR3 expression with high-avidity clones and tumor infiltration." (PMID 37280206, 2023). "As a result, CXCR3 correlates with poor patient survival and metastasis through the activation of cell processes that promote tumour cell proliferation, survival and migration." (PMID 37170733, 2023). "Cxcr3 promoted the differentiation of Klrg1 + PDA-specific T cells in the spleen of tumor-bearing mice, consistent with Cxcr3 promoting short-lived effector T cells in acute infection models." (PMID 36472588, 2023). "CXCL10, encoding chemokines of the CXC subfamily and ligand for the receptor CXCR3, plays a role in some biological activities, which are relevant to various human diseases, such as dysfunction of immune and tumor development." (PMID 37198617, 2023). "Cxcr3 promotes T cell migration and PD-1 blockade efficacy in subcutaneous implantable tumor animal models." (PMID 36472588, 2023). "The CXCL10/CXCR3 axis has therapeutic potential by regulating angiogenesis, recruiting activated immune cells, and influencing the development of tumor cells, which in turn affects the TME." (PMID 37503314, 2023).